IL1B (interleukin 1 beta)
Diseases named in the same sentence as IL1B in open-access papers (continued):
Sharing a sentence is not in itself a finding about the gene and the disease.
tumor (continued). "Additionally, canakinumab reduces tumor cell migration to bone by blocking IL-1β from binding to its receptor, significantly decreasing the incidence and progression of breast cancer bone metastases." (PMID 40873591, 2025). "The inflammatory process in GBM is driven by complex interactions between tumor cells and the tumor microenvironment, which involve changes in the concentration and activity of numerous cytokines and chemokines, including IL-6, IL-1β, and tumor necrosis factor α (TNF-α)." (PMID 40497976, 2025). "Likewise, enhanced HO-1 expression inhibits tumor growth by downregulating matrix metalloproteinases and inflammatory mediators, such as IL-1β, in NCI-H292 mucoepidermoid carcinoma–xenograft models." (PMID 40722961, 2025). "The interplay between AIM2 and the tumor microenvironment also warrants attention, as AIM2 has been implicated in enhancing immune responses against tumor cells, potentially through the activation of pro-inflammatory cytokines like IL-1β." (PMID 40386782, 2025). "Additionally, cancer-associated fibroblasts respond to DAMPs by activating the inflammasome and releasing IL-1β, amplifying pro-inflammatory signalling in the tumour stroma." (PMID 40943351, 2025). "Additionally, CAFs‐derived IL‐1β activates the NF‐kB pathway in tumor cells, driving the release of CCL22 and thereby recruiting Tregs in head and neck cancer." (PMID 41164803, 2025). "IL-1β promotes the growth and migration of tumors by influencing the differentiation of epithelial cells, the secretion of angiogenic molecules, and the expression of adhesion molecules, thus increasing tumor angiogenesis." (PMID 40244135, 2025). "Additionally, certain cytokines like PGE2 and IL-1β interact closely with TAMs in the tumor microenvironment, positioning the PGE2—IL-1β axis as a promising therapeutic target for PDAC." (PMID 40102723, 2025). "IL-1β enhanced accumulation of neutrophils, which accelerates tumor progression." (PMID 40165901, 2025). "Zymosan also enhances IL-1β secretion in OSCC cells through the NLRP3/IL-1β pathway, an inflammatory response that may contribute to tumor progression and potentially affect treatment outcomes." (PMID 41322070, 2025). "Moreover, ELISA quantification confirmed a significant decrease in the pro‐inflammatory cytokines TNF‐α and IL‐1β in tumor tissues following FPHPE administration." (PMID 41200213, 2025). "Injection of mice with IL-1β-secreting tumour cells increases hepatic Slc2a3 expression." (PMID 39433211, 2025). "Notably, ITGB8 + macrophages exhibited elevated levels of pro-tumorigenic markers associated with M2-like tumor-associated macrophages, including FN1, IL1β, CCL4L2, and CCL3L1." (PMID 39743547, 2025). "Furthermore, we identified a significant increase in interleukins and tumour necrosis factors, including IL‐1a, IL‐1b, IL‐6, IL‐17C, IL‐32, IL‐36G and TNF, along with its associated enzyme." (PMID 39865778, 2025). "Consistent with these mechanistic insights, clinical analyses revealed that elevated levels of SAA1, IL1B, and CD33+ MDSCs were significantly correlated with poorer overall survival in EOC patients, underscoring the SAA1/IL-1β/MDSC axis as a key driver of tumor progression and adverse prognosis." (PMID 41029721, 2025). "However, cytokines secreted by tumor cells, such as G-CSF, IL-1β, IL-6, and TNF, can extend their longevity." (PMID 41280929, 2025). "Moreover, NF‐κB activity‐induced expression of the pro‐inflammatory cytokines IL‐1β, IL‐6 and TNFα were also elevated in the hippocampus of these tumour‐bearing mice." (PMID 40172096, 2025). "Within the TME, neutrophils exert a crucial function by secreting IL-1β 35, which acts as an important autocrine signal to sustain an intense recruitment of neutrophils to promote the complex interplay of immune responses and tumor progression." (PMID 40959269, 2025).
tumor (continued). "Furthermore, IL-1β has been shown to contribute to the development of a chronic inflammatory environment in breast cancer, which can support tumor progression." (PMID 40486614, 2025). "Similarly, miR-127 enhances the expression of pro-inflammatory cytokines like IL-6 and IL-1β, suggesting its potential role in promoting an M1 phenotype, which is geared towards fighting infections and tumor cells." (PMID 40821768, 2025). "Besides, the expression of IL-1β and IL-18 in tumor tissues was also evaluated by immunohistochemical analysis." (PMID 40604924, 2025). "In terms of tumor metastasis, Saa3 in a mouse model has been shown to promote the lung metastasis of hepatocellular carcinoma through the formation of pre-metastatic niche, an action requiring IL-1β-induced Saa3 expression." (PMID 39940756, 2025). "Moreover, the expression of genes associated with apoptosis (Bax and Bcl2) and inflammation (Il6 and IL1b) in tumor tissues was notably modulated by rapamycin." (PMID 40361560, 2025). "They further corroborated their studies by demonstrating that blockade of IL-1β signaling significantly decreases tumor angiogenesis in C57B16 IL-1β knockout mice compared to wild-type and IL-1α knockout mice, highlighting the importance of IL-1β in promoting angiogenesis in cancer cells." (PMID 39858071, 2025). "Additionally, IL-1β can impair the function of dendritic cells (DCs), preventing them from effectively presenting tumor antigens and activating T cells." (PMID 41415279, 2025). "Interestingly, tumour and microenvironment-derived IL-1B has the opposite effect in the primary tumour, where infiltration of anti-tumour immune cells impairs tumour growth." (PMID 41091336, 2025). "In a recent study it was found that Chimeric Antigen Receptor T cell (CAR-T) treatment led to the activation of AIM2 in macrophages and the ensuing release of IL-1β both by inducing the α1- adrenergic receptor (α1-AR)-mediated adrenergic signaling and by releasing tumor cell DNA." (PMID 40002808, 2025). "In a recent study, Fahmy and co-workers explored the modulatory impact of B. longum (BL), which was isolated from women’s breast milk samples, on selected oncomiR and tumor-suppressor miRNA, as well as on IL-1β and IL-6-targeted miRNA, employing the mice model of inflammation-induced CRC." (PMID 40519767, 2025). "Expression of the cytokine IL1β remained low in HPVI6-related OPSCC tumor cells." (PMID 41401057, 2025). "Interestingly, an amplification loop that involves γδ T cells‐IL‐17 and myeloid cells‐IL‐1β has been demonstrated to promote tumor growth." (PMID 38703051, 2024). "They found increased IL-6, IL-1β, MDSCs, and tumor regrowth." (PMID 38543305, 2024). "In addition, studies has shown that IL-1α and IL-1β act as tumor-specific Th1 mediators in the fight against cancer." (PMID 38745115, 2024). "Activated B cells are known to secrete inflammatory cytokines such as IL-6, Il-1α, TNF-α and Il-1β itself, which may stimulate IL-β secretion and NfκB activation in tumor cells." (PMID 39801513, 2024). "Additionally, tumor cells exposed to IL-1β and IL-6 acquire an invasive and chemoresistant phenotype." (PMID 39260693, 2024). "In addition, positive feedback in the tumor microenvironment promotes the levels of IL-1β and, unfortunately, carcinogenesis." (PMID 38990306, 2024). "Furthermore, damage-associated molecular patterns (DAMPs) released from necrotic cells stimulate IL-1β expression in TAMs with an autocrine/paracrine feedback loop that accelerates TAMs migration and tumor growth." (PMID 38397187, 2024). "However, when cell pyroptosis occurs, cytokines such as IL-1β and interleukin 6 (IL-6) are released into the tumor microenvironment." (PMID 39526199, 2024). "Moreover, we elucidate a new neuron-glia paracrine circuit, in which neuronal glutamate stimulates oligodendrocyte IL-1β production to result in TAM Ccl5-mediated tumor growth." (PMID 38308315, 2024).
tumor (continued). "Besides, Elisa results of tumor tissue displayed that compared with tumor model group, the levels of IL-1β and IL-18 in XRZYBXD high dose group were increased." (PMID 40046008, 2024). "It is worth noting that the depletion of IL-1β during tumor cell pyroptosis significantly attenuates antitumor immunity, suggesting that IL-1α may not play a major role in inducing antitumor immunity." (PMID 38391959, 2024). "IL-1β is considered to be the quintessential multifunctional cytokine, and its overexpression may contribute to tumorigenesis and promote tumor invasion." (PMID 39795180, 2024). "Consequently, IL1B+ TAMs actively recruit and modulate immune cells thereby orchestrating the inflammatory responses essential for eradicating tumor cells." (PMID 39232806, 2024). "Additionally, we observed that usenamine A increased ROS levels in tumor tissues and elevated levels of IL-1β and IL-18 in serum (p < 0.01)." (PMID 38265972, 2024). "The hypothesis predicts that blockade of IL-6 and its companion cytokines, TNF-α, and IL-1β, will convert an immunologically “cold” (unresponsive) tumor to one that is “hot” (immune responsive)." (PMID 39512605, 2024). "In BCP, IL-1β is consistently upregulated after tumor cell inoculation." (PMID 38940936, 2024). "Additionally, higher level of IL-1β stimulates tumor angiogenesis to accelerate metastasis by activating vascular endothelial growth factors (VEGF)." (PMID 38444674, 2024). "Scholars have stated that kefir reduces tumor cell viability and growth rates, regulates cytokine expression in tumor tissues (e.g., downregulates IL-6, IL-10 and IL-1β, upregulates TNF-α, IL-10, and IL-4), promotes apoptosis, and exerts immune-enhancing effects." (PMID 39605907, 2024). "Furthermore, we used spatial transcriptome analysis to validate the spatial distribution of the various populations of MCs, where MC4 clustered at the tumor-normal interface and colocalized with IL1B+ macrophages." (PMID 39840068, 2024). "Furthermore, our findings indicate CXCL1 chemokine as a strong candidate as a tissue differentiating biomarker and tumor histological stage indicator from patients’ serum, and IL1b overexpression as a molecular factor related to increased TNM stage." (PMID 38175424, 2024). "Thus, our results show that the increase in serum concentration of IL-1β is related to the inhibition of tumor growth/edema in the paws of mice." (PMID 38774541, 2024). "In particular, specific laboratory studies should be conducted to understand whether sustained release of IL-1β can promote tumor progression." (PMID 38799474, 2024). "The addition of IL-1RA during co-culture significantly inhibited the activation of both MMP-2 and MMP-9 in SUM159 cells and suppressed MMP-2 activity in MCF12A cells These results underscore the role of IL-1β signaling in promoting tumor cell invasiveness and MMP activation in TNBC." (PMID 39801513, 2024). "In fact, given that treatment-induced IL-1β seems to promote tumor clearance, IL-1β antagonists during treatment may be detrimental and attenuate antitumor adaptive immune responses." (PMID 38391959, 2024). "Nevertheless, TIB-driven increases in IL-1β may have a paradoxical inhibitory effect on tumor immunity." (PMID 39801513, 2024). "Additionally, genes, associated with inflammasome and cell death including tumor suppressive TNF signaling pathways were upregulated in the samples treated with NT GSDMD + IL-1β + IL-18." (PMID 39737979, 2024). "Interestingly, previous studies have shown that EO771 tumors are dependent on IL-1β derived from the myeloid compartment in the tumor, which drives tumor progression, and that treatment with an IL-1 receptor antagonist inhibited tumor growth." (PMID 39224600, 2024). "Limiting the level of IL-1β may have indirect effects related to its influence on the NF-κB pathway and tumor development." (PMID 39519642, 2024).
tumor (continued). "Patients with high IL-1β expression may have larger tumor size, poorer differentiation, and a higher number of lymph node metastases compared with the low expression group (P < 0.05)." (PMID 38762529, 2024). "Further study is needed to understand the mechanism driving IL-1β expression in tumor cells." (PMID 39801513, 2024). "Tumor infiltrating B cells correlate with IL-1β and microinvasion in TN DCIS." (PMID 39801513, 2024). "In obesity, AT produces elevated levels of estrogen, pro-inflammatory cytokines (TNFα, IL-6, IL-1β), adipokines (leptin), and EVs, which may contribute to enhanced tumor invasiveness, proliferation, and metastasis." (PMID 39697630, 2024). "Additionally, it significantly inhibits the expression of NF-κB signaling-dependent proinflammatory genes IL-6 and IL-1B through RAD51, thus blocking the STING-associated anti-tumor immunity in stromal tumor-infiltrating lymphocytes (sTIL)." (PMID 39638799, 2024). "Mechanistically, IL-1β spurs tumor growth by activating MAPK/NF-κB pathways, recruiting immunosuppressive cells, promoting inflammation, angiogenesis, invasion and metastasis, downregulating tumor suppressors, upregulating oncogenes, and enabling immune evasion and inhibition of apoptosis." (PMID 38957317, 2024). "Th17 cells, regulated by IL-1β, could suppress tumor growth by inducing the expression of chemokines, activating, and recruiting cells such as DCs." (PMID 39252305, 2024). "Of note, IL-1β is a key inflammatory cytokine and has recognised roles in tumour pathogenesis." (PMID 38480935, 2024). "As in vitro 2D cell culture often lacks many features of cancer development, to test if the IL-1β increase could impact the tumor growth, such as hypoxia, altered metabolism, or cell contact, we cultured 3D spheroids to better mimic the in vivo context." (PMID 38672578, 2024). "IL-1β is induced by inflammatory signals in immune cells, and sustained IL-1β production may promote both tumor induction and subsequent tumor propagation." (PMID 39726047, 2024). "Statistical significance could be demonstrated in ‘Ki-67+ and IL-1β+’ for vascular invasion and in ‘Ki-67+ or IL-1β+’ and (higher) tumor grade." (PMID 38397123, 2024). "Additionally, CDK9i evoked the expression of these genes while decreasing those associated with inflammation and tumor killing (e.g., TNF and IL1B)." (PMID 39254172, 2024). "The tumor microenvironment (TME) is a critical source for factors like hypoxia (HIF-1α, NO), and signaling proteins derived from cells such as cancer-associated fibroblasts and macrophages (TGFβ, LCN2, IL-6, IL-1β, etc.)that influence EMT50." (PMID 39737957, 2024). "A few studies have suggested that blocking the NLRP3 inflammasome/IL-1β pathway may be a potential strategy for treating HNSCC by ameliorating the tumor microenvironment." (PMID 38904007, 2024). "Pharmacological inhibition of NLRP3 inflammasome using MCC950, followed by PTX administration decreased the pro-inflammatory processes associated with anti-tumor treatment as indicated by the expression of NLRP3, caspase-1, IL-1β and IL-18, compared with PTX treatment." (PMID 39433537, 2024). "During RT pyroptosis could lead to the release of immune factors such as IL-18 and IL-1β, which in turn facilitate the promotion of anti-tumor immunity." (PMID 38228635, 2024). "Moreover, contact between tumor cells and osteoblasts or bone marrow cells can increase IL-1β secretion from all three cell types." (PMID 38334625, 2024). "However, due to the complex repercussions on the course of cancer, both tumor-promoting and inhibitory functions of IL-1β have been described; its specific role in BC carcinogenesis is yet to be determined." (PMID 38397123, 2024). "Additionally, targeting pro-inflammatory macrophages and blocking IL-1β signaling in tumor cells has been suggested to inhibit tumor growth." (PMID 39068459, 2024).
tumor (continued). "The interplay between UPP1high tumor cells and SPP1+ macrophages was linked with a variety of chemokines, including CCL2_CCR2, CCL3_CCR5, CXCL3_CXCR2, and CXCL8_CXCR1, as well as interactions such as IL1B_IL1_receptor and TGFB1_TGFbeta_receptor1." (PMID 38331898, 2024). "This suggests that outgrowth of virulent S. aureus may stimulate the tumour microenvironment to activate malignant T cells via IL-1B in a paracrine fashion." (PMID 39682136, 2024). "Interestingly, IL-15, IL-18, and IL-1β cytokine profiles reveal a significant host serum increase after day 35 when the tumor began to progress in growth (respectively)." (PMID 39451257, 2024). "IL-1β signaling on T cells promotes the production of IL-17, which may in turn attract immature myeloid cells to the tumor." (PMID 38898209, 2024). "Furthermore, spatial transcriptomics data revealed that IL1B+ macrophages also clustered at the tumor-normal interface in ccRCC, which is consistent with previous reports." (PMID 39840068, 2024). "Resident LAM-APOC1 was expressed both in the tumor and juxta-tumor area, strongly associated with CD8+ T cells and T-regs, while LAM-STAB1 was mostly expressed in the tumor and had a high level of TREM2 and IL-1B, suggesting their monocytic origin associated with poor prognosis." (PMID 39104525, 2024). "Thus, tumor spheroids were generated using Hep3B cells (104 cells), incubated in the presence of sorafenib (1 μM), and the effect of IL-1β (0.25 μg/mL) was analyzed." (PMID 38672578, 2024). "Moreover, SPP1 + Mac-derived TNF-α and IL-1β promoted the expression of OPN in both tumor cells and other adjacent macrophages through different signaling pathways." (PMID 39726047, 2024). "However, this induction was clearly enhanced by the presence of tumor cells (tnfa, 17.3-fold increase; il1b, 30.3-fold increase; il6, 30.7-fold increase)." (PMID 39114912, 2024). "Studies have identified CCL8 and IL-1b as key factors in the recruitment and immunosuppression of TAMs in tumor hypoxia, suggesting that targeting these cytokines could improve treatment outcomes." (PMID 39068459, 2024). "Moreover, pro-inflammation cytokines, such as Il1b, Il12b and Il18, were upregulated in the tumor of Il21r−/− mice; whereas anti-inflammation cytokines, including Il10 and Il22 were decreased in the tumor of Il21r−/− mice." (PMID 38720319, 2024). "Moreover, stimulation with mouse-derived recombinant SPP1 protein induced the expression of pro-tumor genes (such as Arg1, Slc2a1, and Nos2) in MDSCs while repressing the expression of anti-tumor genes (such as Il1b, Tnfa, and Il12b)." (PMID 39066845, 2024). "Interestingly, ATP can bind to the P2X7 receptor on DCs to promote the secretion of IL‐1β by DCs, and the establishment of a positive cycle strengthens the anti‐tumour immune environment." (PMID 38652105, 2024). "There is emerging evidence that tumour derived IL-1β drives the IL-6/STAT3 axis and thus may act as a master cytokine to increase other transcription factors." (PMID 39516433, 2024). "In studies on tumors, resveratrol has been proven to downregulate the production of pro-inflammatory cytokines, such as TNF-α, IL-6, and IL-1β, and mitigating the inflammatory milieu within the tumor microenvironment hinders the development of angiogenesis, tissue invasion, and metastasis processes." (PMID 39458478, 2024). "To assess whether TNBC cell lines could express activated IL-1β, we performed western blot analysis to detect cleaved caspase 1 in tumor cell lines both before and after co-culture with EBV-transformed B cells." (PMID 39801513, 2024). "In circumstances of associated chronic inflammation, the formation of pro-inflammatory cytokines stimulates the infiltration of cytotoxic T lymphocytes (CTLs) into the tumor, whereas IL-1β and IL-2 cytokines boost the migration of immunosuppressive MDSCs and Treg cells." (PMID 38745115, 2024).